ANTKMT (adenine nucleotide translocase lysine methyltransferase)
Description:
Mitochondrial protein-lysine N-methyltransferase that trimethylates adenine nucleotide translocases ANT2/SLC25A5 and ANT3/SLC25A6, thereby regulating mitochondrial respiration. Probably also trimethylates ANT1/SLC25A4.
Synonyms: ANT-KMT; C16orf24; FAM173A; MGC2494
Tractability: Antibody: UniProt predicts a signal peptide or a membrane-spanning region.
Gene: Protein-coding gene on chromosome 16 (720,581 to 722,590, forward strand). Ensembl gene ENSG00000103254.
Subcellular location: Mitochondrion membrane
Subcellular location (Human Protein Atlas): Cytosol
Gene Ontology:
Molecular function: protein binding; protein-lysine N-methyltransferase activity
Biological process: peptidyl-lysine trimethylation; regulation of mitochondrial ATP synthesis coupled proton transport
Cellular component: mitochondrial membrane; mitochondrion
Genetic constraint (gnomAD): Loss-of-function variants: 25 observed, 15.16 expected, observed/expected ratio (o/e) 1.65, 90% interval 1.17 to 1.95. The synonymous counts are far from expectation, so gnomAD's model fits this gene poorly and the ratio says little. Missense variants: 428 observed, 280.01 expected, observed/expected ratio (o/e) 1.53, 90% interval 1.41 to 1.66. Synonymous variants: 193 observed, 133.17 expected, observed/expected ratio (o/e) 1.45, 90% interval 1.29 to 1.63.
Homologues: Orthologues: chimpanzee ANTKMT (97% identical), macaque ANTKMT (90% identical), dog ANTKMT (82% identical), pig ANTKMT (81% identical), guinea pig ANTKMT (80% identical), rat Antkmt (80% identical), mouse Antkmt (78% identical), tropical clawed frog antkmt (57% identical), zebrafish antkmt (52% identical), Drosophila melanogaster CG3337 (30% identical), Caenorhabditis elegans Y39A1A.21 (26% identical). Paralogues in human: ATPSCKMT (37% identical).
Diseases named in the same sentence as ANTKMT in open-access papers:
ANTKMT is named in the same sentence as 1 disease in open-access papers, as found by Europe PMC text mining. Sharing a sentence is not in itself a finding about the gene and the disease. The quoted sentences say what the papers report.
lung carcinoma (1 paper, 2025). "Additionally, ANTKMT (also known as FAM173A), a mitochondrial lysine (K)–specific methyltransferase, and TNF receptor–associated factor 6, a ubiquitin ligase bridging the RAS and NF-κB pathways in lung cancers, were also significantly downregulated." (PMID 39437162, 2025).